SYNC (syncoilin, intermediate filament protein)
Description:
Atypical type III intermediate filament (IF) protein that may play a supportive role in the efficient coupling of mechanical stress between the myofibril and fiber exterior. May facilitate lateral force transmission during skeletal muscle contraction. Does not form homofilaments nor heterofilaments with other IF proteins.
Synonyms: SYNC1; SYNCOILIN
Tractability: Antibody: its Gene Ontology location is reachable by antibodies, with medium confidence; the Human Protein Atlas places it where antibodies can reach.
Gene: Protein-coding gene on chromosome 1 (32,679,906 to 32,703,596, reverse strand). Ensembl gene ENSG00000162520.
Subcellular location: Cytoplasm, perinuclear region
Subcellular location (Human Protein Atlas): Plasma membrane; Golgi apparatus; Vesicles
Gene Ontology:
Molecular function: protein binding
Biological process: intermediate filament-based process
Cellular component: cytosol; neuromuscular junction; sarcolemma; Z disc; cytoplasm; intermediate filament; perinuclear region of cytoplasm
Genetic constraint (gnomAD): Loss-of-function variants: 38 observed, 49.22 expected, observed/expected ratio (o/e) 0.77, 90% interval 0.6 to 1.01. The upper end of that interval is the gene's LOEUF score, 1.01, which puts it in group 4 of 6, group 1 being the genes least tolerant of losing a copy. Missense variants: 579 observed, 593.31 expected, observed/expected ratio (o/e) 0.98, 90% interval 0.91 to 1.04. Synonymous variants: 201 observed, 235.04 expected, observed/expected ratio (o/e) 0.86, 90% interval 0.76 to 0.96.
Homologues: Orthologues: chimpanzee SYNC (95% identical), macaque SYNC (87% identical), pig SYNC (84% identical), dog SYNC (81% identical), guinea pig SYNC (79% identical), mouse Sync (77% identical), rat Sync (76% identical), rabbit SYNC (73% identical), tropical clawed frog sync (31% identical), zebrafish sync (23% identical).
Diseases named in the same sentence as SYNC in open-access papers:
SYNC is named in the same sentence as 5 diseases in open-access papers, as found by Europe PMC text mining. Sharing a sentence is not in itself a finding about the gene and the disease. The quoted sentences say what the papers report.
gastric cancer (1 paper, 2025). A primary or metastatic malignant neoplasm involving the stomach. "Finally, SYNC is elevated in human gastric cancers and interestingly has also been correlated to poorer survival outcomes and infiltration of M2-polarized tumor-associated macrophages." (PMID 40352330, 2025).
Insulin resistance (1 paper, 2019). Increased resistance towards insulin, that is, diminished effectiveness of insulin in reducing blood glucose levels. "Solute carrier family 38, member 10 (SLC38A10), SYNC, and DMRT3 are novel biomarkers for the development of insulin resistance." (PMID 30678306, 2019).
tumor (3 papers, 2018 to 2025). "We found two genes, syncoilin (SYNC) and chymotrypsinogen B2 (CTRB2), to discriminate between tumor and non-tumor tissue in data set M1 (blue line)." (PMID 29675033, 2018).
cardiovascular diseases (1 paper, 2023). "Additionally, some of the predicted genes, including BCL6, LDB3, MUC1 and SYNC, have been implicated in other cardiovascular diseases." (PMID 38100461, 2023).
neuromuscular disease (1 paper, 2022). "The trans gene SYNC was found to interact with dystrobrevin (DMD gene) in order to maintain muscle function (during contraction) in mice as well as being associated with neuromuscular disease." (PMID 36344995, 2022).